HIF1A (hypoxia inducible factor 1 subunit alpha)
Diseases named in the same sentence as HIF1A in open-access papers (continued):
Sharing a sentence is not in itself a finding about the gene and the disease.
Hyperglycemia (continued). "Results showed a statistically significant increase in HIF1α activity in the case of the 1BR.3.N WWOX KO transductant compared to the 1BR.3.N CONTR under the conditions of normoxia normoglycemia (p < 0.01), normoxia hyperglycemia (p < 0.05) and hypoxia hyperglycemia (p < 0.01)." (PMID 35328751, 2022). "Data regarding the kidneys suggest that hyperglycemia may lead to an abnormal metabolism with high hexokinase and pyruvate kinase M2 activity, low Sirtuin-3 levels, an activated STAT3, and HIF1α signaling and an aberrant glycolysis similar to the Warburg effect in cancer cells." (PMID 34778040, 2021). "Notably, hyperglycemia can decrease the stability of HIF-1α, leading to the inhibition of HIF-1α target gene expression, which could account for the poor healing and ulcer complications in diabetic patients." (PMID 34099651, 2021). "Prolonged exposure to hyperglycemia also impairs endothelial function by downregulating endothelial NOS expression, which inhibits HIF1α accumulation, and by increasing the production of ROS and reactive nitrogen species (RNS), which promote HIF1α degradation by activating PHDs." (PMID 34290616, 2021). "Thus, this study focused on whether HIF-1α and histone demethylase JMJD1A were key participants in mediating the damaging effects of ECs on inflammation and oxidative stress in hyperglycemia and hypoxia and on their interaction." (PMID 34479471, 2021). "However, under hyperglycaemia, SP1 siRNA, ROBO4 siRNA and miR‐125b‐5p could protect against HG‐stimulated RPE migration, and HIF‐1α siRNA, ROBO4 siRNA and miR‐146a‐5p could also prevent hypoxia‐induced RPE migration." (PMID 31094072, 2019). "There are 3 patients with negative HIF-1α in euglycemia group and 1 in hyperglycemia group." (PMID 30455857, 2018). "However, the link between hyperglycemia induced increases in oxidative stress and decreases in myocardial HIF-1α in the context of myocardial ischemia-reperfusion has not been elucidated." (PMID 23874823, 2013). "Therefore, we found, for the first time, that salidroside could cancelled the hyperglycemia-induced PHD3 accumulation in the skeletal muscle cells, which resulted in the restoration of HIF-1α protein accumulation and angiogenic factors expression, especially VEGF-A and PDGF-BB." (PMID 29228603, 2017). "Furthermore, cotreatment with Hcy 53, further increased HIF-1α levels in hyperglycemia-induced HUVECs compared to Set7_1a alone, demonstrating that Hcy could enhance the potency of Set7_1a to induce the stabilization of HIF-1α but not affecting the level of SET7/9." (PMID 35859119, 2022). "In the co-IP results, Set7_1a did not decrease the amount of HIF-1α coprecipitating with SET7/9 in hyperglycemia-induced HUVECs in hypoxia, indicating that it did not affect the interaction of SET7/9 and HIF-1α in the treated cells." (PMID 35859119, 2022). "Furthermore, in normoxia hyperglycemia, our results showed that WWOX over-expression stabilizes high HIF1α protein amount without changes in its mRNA expression and protein localization." (PMID 35328751, 2022). "Although neither GLUT3 nor HIF-1α expression was altered under hyperglycemic conditions, the PM-bound GLUT3 level was significantly reduced by hyperglycemia treatment, and consistent with this finding, glucose uptake was almost entirely eliminated under high-glucose conditions." (PMID 34796169, 2021). "To test whether in vivo hyperglycaemia also induces hypoxia and activates HIF in pancreatic islets, we first measured HIF1α protein levels in islets from diabetic Leprdb/db and non-diabetic Leprdb/+ mice." (PMID 22235342, 2012).
Sepsis (159 papers, 2012 to 2026). Sepsis is defined as life-threatening organ dysfunction caused by a dysregulated host response to infection. "Bidirectional regulation of HIF-1α in sepsis-associated ARDS reflects the body's dynamic adaptation to hypoxia and inflammation." (PMID 40887582, 2025). "Previous studies have also revealed that the related role of PI3K/Akt, ERK, TLR4/NF-κB, and HIF-1α involved in sepsis-associated inflammation and cardiac injury." (PMID 41311552, 2025). "Future research should focus on elucidating the specific molecular mechanisms and pathways through which HIF-1α contributes to the pathogenesis of sepsis-associated ARDS." (PMID 40887582, 2025). "LPS upregulates miR-208a-5p in sepsis, which has been shown to activate the NF-κB/HIF-1α axis mediated by SOCS2, causing mitochondrial swelling and ultimately leading to cardiomyocyte apoptosis." (PMID 40041174, 2025). "For instance, HIF1A is crucial in inflammation and angiogenesis, with changes in its expression levels potentially linked to the severity and prognosis of sepsis." (PMID 40672940, 2025). "By exploring the therapeutic potential of targeting HIF-1α, this review seeks to offer valuable insights into the underlying mechanisms linking sepsis to ARDS." (PMID 40887582, 2025). "In this study, HIF-1α was identified as a key factor influencing the development and prognosis of sepsis-associated ARDS, demonstrating dual roles in both promoting and mitigating disease progression." (PMID 40887582, 2025). "Promising experiments have showed that HIF-1α plays an important role in the inflammatory regulation and organ dysfunction associated with sepsis." (PMID 41311552, 2025). "HIF-1α has emerged as a potential therapeutic target in various human diseases, including sepsis, a heterogenous syndrome and a common cause of ARDS." (PMID 39791730, 2024). "Recent clinical studies have shifted focus toward translating HIF-1α research findings from basic science to clinical applications, emphasizing its relevance in post-diagnostic and prognostic aspects of sepsis." (PMID 38539163, 2024). "As downstream targets of HIF-1α, hexokinases are implicated in the reprogramming of glucose metabolism during sepsis-induced lung injury." (PMID 39712019, 2024). "Bioinformatics research has pinpointed HIF-1α messenger ribonucleic acid (mRNA) as a potential autophagy-related gene associated with sepsis-associated ARDS." (PMID 38539163, 2024). "After cecal ligation and puncture (CLP) in mice, leading to lethal polymicrobial sepsis, bulk liver RNA sequencing illustrated the induction of the genes encoding HIF1α and HIF2α, and an enrichment of HIF-dependent gene signatures." (PMID 37006237, 2023). "PMN transcriptomics identified HIF-1α as the LDHA-associated signaling pathway in neutrophils during sepsis." (PMID 35090526, 2022). "Among 5,607 DEGs, Lrg1, Ace2, Itgb6, Hmgb2, Pik3r5, Itgam, Plcb1, Jak2, Vegfa, and Hif1α were associated with the entire course of sepsis-induced myocardial injury, which have been reported previously." (PMID 35721566, 2022). "We here determined the role of myeloid cell HIF1α in the host response during pneumonia and sepsis caused by the common human pathogen Klebsiella pneumoniae." (PMID 34393650, 2021). "In sepsis-induced thrombus formation, HIF-1α activation is associated with NET formation during thrombosis, suggesting that NETs are downstream factors of hypoperfusion." (PMID 33672844, 2021). "We here report that HIF1α deficiency in myeloid cells results in enhanced bacterial growth in pneumonia and sepsis caused by K. pneumoniae." (PMID 34393650, 2021). "The induction of HIF1α in response to sepsis-associated cytopathic hypoxia has also been shown in previous human adult and mouse sepsis studies." (PMID 32479514, 2020). "The progression of lipopolysaccharide-induced sepsis is less severe in HIF-1α-deficient mice, as compared to that in wild-type." (PMID 30609861, 2019).
Sepsis (continued). "Using an in vitro model of sepsis the mechanism underlying the switch from HIF-1α dependent glycolysis in the early phase of sepsis to PGC-1 dependent fatty acid β oxidation during the late response to sepsis has been explored in macrophages." (PMID 31555665, 2019). "Collectively, this data shows that HIF-1α contributes to the pathogenic role of macrophages in sepsis pathology." (PMID 31555665, 2019). "For example, neutrophil gelatinase-associated lipocalin has demonstrated early predictive power for AKI in various clinical scenarios such as cardiac surgery and sepsis, providing strong evidence for exploring key regulatory molecules like HIF-1α as early diagnostic markers." (PMID 41602837, 2026). "This implies that reduced HIF-1α levels may be associated with more severe sepsis, suggesting that HIF-1α expression may reflect the body’s capacity to respond to pathological conditions." (PMID 41562069, 2025). "Thus, elevated HIF-1α not only mitigates energy failure but also suppresses inflammation, reducing the incidence of sepsis-associated ARDS." (PMID 40887582, 2025). "By targeting key pathways such as PI3K/Akt/mTOR and HIF-1α, and integrating the role of the microbiome, more effective and personalized treatment strategies can be formulated to address the complex metabolic challenges associated with sepsis." (PMID 41041277, 2025). "Further research highlighted the use of HIF-1α, combined with other clinical parameters, as a tool for sepsis diagnosis, demonstrating high diagnostic accuracy (AUC 0.926, 95% CI 0.885–0.968) and revealing a U-shaped relationship between HIF-1α levels and ICU mortality." (PMID 38539163, 2024). "Furthermore, TASE decreased the HIF-1α pathway-associated genes IRAK-M, VEGFA and PD-L1 in sepsis cells, suggesting HIF-1α inhibition by TASE leads to higher cytokine production in these cells as a consequence of IRAK-M downregulation." (PMID 37047205, 2023). "Sepsis increased plasma levels of inflammatory mediators, oxidative stress markers and HIF-1α expression; caused pathological damage; increased permeability (P < 0.05); and decreased TJ protein expression in the intestinal mucosa of rats with sepsis (P < 0.05)." (PMID 35576220, 2022). "Another study showed that miR-208a-5p was increased in the myocardium during sepsis and its inhibition could reduce the myocardial damage caused by inflammation, probably by affecting the NF-κB/HIF-1α pathway." (PMID 36012630, 2022). "HIF-1a activation protected the intestinal mucosal barrier by reducing intestinal mucosal permeability and regulating Claudin-1, a TJ protein, and then alleviated the damage to the intestinal mucosal barrier caused by sepsis; while a HIF-1α inhibition had the opposite effects." (PMID 35576220, 2022). "Our findings suggest that altered levels of plasma miRNA in CAP‐associated sepsis (relative to controls) may influence various canonical signalling pathways, notably HIF‐1α signalling, hippo signalling and proteoglycan reactions." (PMID 34272809, 2021). "In consistent with previous observation of PKM2-HIF-1α metabolic pathway that promote AIM and NLRP3 inflammasome activation, the HIF-1α-mediated anaerobic glycolysis upregulated after depletion of neurotransmitter-mediated immune responses showed association with sepsis lethality." (PMID 34824200, 2021). "Moreover, previous studies have demonstrated that loss of HIF-1α signaling protects against endotoxemia and sepsis-induced hypothermia." (PMID 32194434, 2020). "HIF-1α mRNA expression was suppressed and conversely associated with disease severity in sepsis." (PMID 29026849, 2017). "Analyzing HIF-1α mRNA expression in the course of sepsis depending on genetic variants might help to understand the regulation of the hypoxic-inflammatory pathway in the critically ill." (PMID 27515179, 2016). "HIF1A mRNA expression is increased in shock patients, and decreased HIF1A mRNA expression in patients with sepsis may be associated with depressed immune function." (PMID 26215820, 2015).
Sepsis (continued). "However, upregulation of HIF-1α promotes glycolysis, compensates for energy deficits caused by mitochondrial dysfunction, prevents ATP depletion, and protects the pulmonary epithelium from energy failure, thereby mitigating the risk of sepsis-associated ARDS." (PMID 40887582, 2025). "As a high SAPS II is associated with increased mortality, one might expect increased mortality in HIF-1α T-allele carriers as well, however one might emphasize that sepsis itself contributes stronger to alterations in HIF-1α mRNA expression than this genetic variant does." (PMID 27515179, 2016). "Specifically, we tested the hypotheses, that SNPs in the HIF-1α or PHD2 genes are 1) common in Caucasians with 2) the HIF-1α genetic variant being associated with an altered HIF-1α mRNA expression, and 3) independent risk factors for 30-day mortality in severe sepsis." (PMID 27515179, 2016). "Existing research has demonstrated that PI3K/Akt signaling pathway is involved in HIF-1α regulation in sepsis, and HIF-1α can be mediated by PI3K/Akt/ERK pathway in retinopathy of prematurity." (PMID 41311552, 2025). "This narrative review delves into the intricate molecular and biological characteristics of HIF-1α, elucidating its regulatory role within the context of sepsis and ARDS." (PMID 40887582, 2025). "This dual function makes regulating HIF-1α in sepsis a complex and challenging task with 2 distinct aspects." (PMID 41041277, 2025). "In mice model, HIF-1α signaling pathway was related to sepsis-induced lung injury, ARDS and encephalopathy." (PMID 39891057, 2025). "At 6 h, HIF-1α levels were relatively higher in the Sepsis-plus-hypoxia group compared to other groups, whereas the Sepsis group showed the lowest expression." (PMID 41422365, 2025). "The excessive release of inflammatory mediators during sepsis can upregulate the expression levels of HIF-1α." (PMID 40887582, 2025). "Considering the significant upregulation of Hif1a across various tissues in sepsis, the role of Hif1a in NTIS cannot be discounted." (PMID 39877839, 2025). "Ultimately, this exploration of HIF-1α seeks to enhance our comprehension of sepsis pathogenesis, identify novel therapeutic avenues, and lay a strong theoretical groundwork for future clinical interventions." (PMID 40887582, 2025). "Targeted therapies aimed at HIF-1α represent a promising strategy for mitigating organ damage in sepsis." (PMID 41041277, 2025). "Some Chinese medicine studies shown that HIF-1α signaling pathway improved the prognosis of sepsis by inhibiting aerobic glycolysis, regulating cell apoptosis, and responding to inflammation and oxidative stress." (PMID 39891057, 2025). "The up-regulation of glycolytic activity mediated by HIF-1α in sepsis not only fulfills the immediate energy demands of immune cells but also has the capacity to influence the overall systemic metabolic milieu." (PMID 41041277, 2025). "The expression trends of AKT1 and HIF1A in COVID-19 patients were consistent with those in sepsis patients." (PMID 41411324, 2025). "The regulatory mechanisms governing metabolic reprogramming involve numerous signaling pathways and regulatory factors, with HIF-1α identified as a key mediator of monocyte metabolic reprogramming during sepsis." (PMID 41562069, 2025). "In the inflammatory response, HIF-1α can modulate it by modulating a variety of inflammatory factors involved in the development of sepsis." (PMID 40887582, 2025). "Future research should investigate the impact of HIF-1α regulation on both inflammation and the metabolic adaptation of immune cells in the context of sepsis." (PMID 41041277, 2025). "HIF-1α expression was lowest in sepsis-only kidneys but markedly upregulated in the sepsis-plus-hypoxia group at 6 h." (PMID 41422365, 2025).
Sepsis (continued). "The latest research reveals that recombinant thrombomodulin (rTM) exerts a protective effect against sepsis by inhibiting the HIF-1α/METTL3/PFKM axis and promoting the transformation of macrophages to an anti-inflammatory phenotype." (PMID 41244772, 2025). "Key signaling pathways—including HIF-1α, mTOR, in various stages of sepsis, relevant pathways play core and interrelated roles." (PMID 41244772, 2025). "Mechanistically, CD38high monocytes in sepsis exhibit hyperactivated glycolysis with activation of hypoxia‐inducible factor‐1α (HIF‐1α) due to NAD+ consumption." (PMID 40145840, 2025). "EGCG reduces EGFR and suppresses HIF-1α, HK2, PKM2, and iNOS expression, thereby attenuating sepsis-associated acute lung injury." (PMID 41322289, 2025). "Previous studies have shown, monocytes generated immunosuppression through HIF-1α signaling pathway in the later phase of sepsis." (PMID 39891057, 2025). "Drawing upon this prior research, the current study delves into the pivotal role of HIF-1α as a key connector between sepsis and ARDS." (PMID 40887582, 2025). "In sepsis models, the accumulation of succinic acid and its induced HIF-1α stabilization are considered important factors in triggering excessive inflammatory responses." (PMID 41488672, 2025). "In previous investigations, our research has encompassed a range of studies examining the involvement and functionality of HIF-1α in sepsis." (PMID 40887582, 2025). "Growth differentiation factor 15 (GDF15) protects against sepsis-induced ALI by suppressing the HIF-1α/LDHA glycolytic axis in pulmonary ECs, thereby reducing cytokine production and leukocyte recruitment." (PMID 41488672, 2025). "The aim of this review is to elucidate the role of HIF-1α and its related mechanisms in the initiation, progression, and immune response of sepsis, as well as to evaluate its potential therapeutic implications." (PMID 38539163, 2024). "In the context of sepsis, medications that reduce HIF-1α activity typically function by inhibiting the DNA transcription and expression of HIF-1α." (PMID 38539163, 2024). "In a recent review, Ruan and colleagues extensively summarised the potential therapeutic value of HIF-1α as a targeted therapy in the setting of sepsis." (PMID 39791730, 2024). "Under hypoxic conditions prevalent in sepsis, HIF-1α serves as a pivotal upstream molecule in glycolysis." (PMID 39712019, 2024). "Modulating HIF-1α-driven immune metabolism via PKM2 offers new potential targets for curbing uncontrolled inflammatory responses in the context of sepsis-induced lung injury." (PMID 39712019, 2024). "Norisoboldine hinders the translocation of PKM2 from the cytoplasm to the nucleus, reducing HIF-1α expression and mitigating sepsis-induced acute lung injury." (PMID 38539163, 2024). "On the other hand, hypoxia-inducible factor-1α (HIF-1α) induces immunosuppression and enhances repair characteristics in classical and intermediate monocytes during active sepsis." (PMID 39408970, 2024). "HIF-1α plays a crucial role in sepsis, and its activation is closely tied not only to intracellular hypoxia but also to the inflammatory process and immune regulation." (PMID 38539163, 2024). "This review aims to furnish a comprehensive overview of HIF-1α's mechanism of action in sepsis, scrutinizing its involvement in inflammatory regulation, hypoxia adaptation, immune response, and organ dysfunction." (PMID 38539163, 2024). "HIF-1α modulation is a potential therapeutic target for chronic inflammatory disorders, including sepsis, as it plays a crucial role in hypoxia-induced inducible nitric oxide synthase expression." (PMID 39200130, 2024). "Various drugs demonstrate protective effects against sepsis-induced damage in different target organs by modulating HIF-1α activity." (PMID 38539163, 2024). "Hypoxia-inducible factor-1α (HIF-1α), a notable transcription factor, assumes a pivotal role in the onset and progression of sepsis." (PMID 38539163, 2024).